IZUMO2 (IZUMO family member 2)
Synonyms: C19orf41; SCRL; MGC33947; PLAL6978; PRO21961
Tractability: Antibody: UniProt predicts a signal peptide or a membrane-spanning region.
Gene: Protein-coding gene on chromosome 19 (50,152,537 to 50,163,281, reverse strand). Ensembl gene ENSG00000161652.
Subcellular location: Membrane
Subcellular location (Human Protein Atlas): Acrosome; Mid piece
Pathways (Reactome):
Reproduction: Acrosome Reaction and Sperm:Oocyte Membrane Binding
Gene Ontology:
Cellular component: membrane
Genetic constraint (gnomAD): Loss-of-function variants: 16 observed, 19.4 expected, observed/expected ratio (o/e) 0.82, 90% interval 0.56 to 1.25. The upper end of that interval is the gene's LOEUF score, 1.25, which puts it in group 5 of 6, group 1 being the genes least tolerant of losing a copy. Missense variants: 221 observed, 222.48 expected, observed/expected ratio (o/e) 0.99, 90% interval 0.89 to 1.11. Synonymous variants: 118 observed, 99.65 expected, observed/expected ratio (o/e) 1.18, 90% interval 1.02 to 1.38.
Homologues: Orthologues: chimpanzee IZUMO2 (99% identical), macaque IZUMO2 (90% identical), rabbit IZUMO2 (73% identical), dog IZUMO2 (69% identical), pig IZUMO2 (66% identical), rat Izumo2 (57% identical), mouse Izumo2 (52% identical).
Diseases named in the same sentence as IZUMO2 in open-access papers:
IZUMO2 is named in the same sentence as 1 disease in open-access papers, as found by Europe PMC text mining. Sharing a sentence is not in itself a finding about the gene and the disease.
IZUMO2 shares sentences with these, for which no sentence is quoted: acute myeloid leukemia (1 paper).